IL6 (interleukin 6)
Diseases named in the same sentence as IL6 in open-access papers (continued):
Sharing a sentence is not in itself a finding about the gene and the disease.
multiple system atrophy (3 papers, 2021 to 2026). Multiple system atrophy (MSA) is a neurodegenerative disorder characterized by autonomic failure (cardiovascular and/or urinary), parkinsonism, cerebellar impairment and corticospinal signs with a median survival of 6-9 years. "Other works revealed increased levels of interferon γ, IL-10, IL-18, IL-1β, IL-4, IL-6, transforming growth factor β1, and Tumor Necrosis Factor-α in PSP and Multiple System Atrophy when compared to PD." (PMID 39176092, 2024). "Patients were followed up at 0, 1, 3, and 6 months after treatment, and the Unified Multiple System Atrophy Rating Scale (UMSARS) scores, TNF-α in the peripheral blood, IL-6, percentage of CD4, and CD4/CD8 ratio were evaluated and compared for each follow-up point; any adverse effects were recorded." (PMID 34900026, 2021).
myelitis (3 papers, 2018 to 2022). An inflammatory process affecting the spinal cord. "There was a tendency(p<0.1) for a higher frequency of myelitis in patientswith increased CSF IL-6 levels in both subgroups and for increased serum GRO-αlevels in MOG-Ab positive children." (PMID 31205739, 2019). "It was suggested that myelitis may occur due to interleukin-6 (IL-6) and interleukin-17 (IL-17) running an inflammatory response leading to cytokine storm." (PMID 36428722, 2022).
Myelopathy (3 papers, 2018 to 2026). Myelopathy is an descriptive term, referring to pathology leading to a neurologic deficit related to the spinal cord. "We discuss current evidence of CAR-T-associated myelopathy, its proposed inflammatory and immune-trafficking mechanisms, and the potential contribution of interleukins and chemokines such as IL-1, IL-6, IL-18, CCL-2 and CXCL10 signaling to spinal cord injury." (PMID 41993175, 2026).
nematode infections (3 papers, 2015 to 2024). "Among these, IL-5 and IL-6 are the most critical cytokines in nematode infections." (PMID 38786064, 2024). "Finally, elevated resistin was associated with higher concentration of IL-6, CCL2 and TNFα and inflammatory factors, suggesting that the resistin/proinflammatory cytokine immune axis we identified in mice is also present in human nematode infections." (PMID 25568944, 2015).
nephrotoxicity (3 papers, 2014 to 2024). Toxicity that causes injury to the kidney or damages its function. "Pioglitazone reduced the mRNA levels of pro-inflammatory cytokines (IL-6 and TNF-α) and increased the mRNA levels of anti-inflammatory cytokines (IL-4 and IL-10) in an in vitro model of calcium oxalate monohydrate-induced nephrotoxicity." (PMID 39621679, 2024).
neuralgia (3 papers, 2015 to 2025). "The median of patients with HZN and neuralgia without HZN of age, NRS score, percentage of CD8+, CD4+/CD8+, IL-6, and galectin-3 were 63.0, 5.0, 29.0, 1.25, 49, and 1.005, respectively." (PMID 32351643, 2020).
neurofibroma (3 papers, 2023 to 2024). An intraneural or extraneural neoplasm arising from nerve tissues and neural sheaths. "IL-6 was heavily expressed by a majority of the fibroblast populations in the neurofibroma; in addition to its role in inflammation, it is thought to be an early indicator of nerve injury." (PMID 37817770, 2023).
neurosyphilis (3 papers, 2024 to 2025). Infection of the brain or spinal cord by Treponema pallidum. "The neuroinflammatory response in neurosyphilis involves the activation of microglia, which release pro-inflammatory cytokines such as tumor necrosis factor-alpha (TNF-α), interleukin-1 beta (IL-1β), and interleukin-6 (IL-6)." (PMID 39728746, 2024). "In addition, studies have shown that the levels of CSF protein and white blood cell count are positively correlated with the inflammatory markers CXCL13, IL-6, and IL-10, which suggests that patients with atypical neurosyphilis may not have a significant or active inflammatory response." (PMID 41376790, 2025).
nicotine dependence (3 papers, 2024 to 2025). Physical and psychological dependence on nicotine. "Second, regarding risky behaviors, nicotine dependence was associated with significantly higher levels of CRP and IL-6, and risky alcohol use was marginally associated with lower IL-1ra (p = 0.08)." (PMID 41267823, 2025). "In our high-risk sample, we found that nicotine dependence was associated with higher levels of pro-inflammatory markers CRP and IL-6, while alcohol use was associated with lower levels of anti-inflammatory marker IL-1ra." (PMID 41267823, 2025). "Furthermore, MDD, morphine dependence, and nicotine dependence share pro-inflammatory cytokines interleukin 6 (IL6), interleukin 1B (IL1B), and tumor necrosis factor (TNF) with progeria syndrome." (PMID 38926475, 2024). "Additionally, higher ELS was associated with higher IL-1ra (r = 0.19), nicotine dependence was positively associated with higher CRP (r = 0.30) and IL-6 (r = 0.36), and physical activity (r = −0.18) and nutrition (r = −0.20) were negatively correlated with IL-6 (all rs p < 0.05)." (PMID 41267823, 2025). "Reported outcomes include pulmonary function (e.g., FEV1), inflammatory and oxidative stress biomarkers (e.g., TNF-α, IL-6, CRP, 8-OHdG), nicotine dependence scores, salivary cotinine levels, oral health indices, and other exposure-related markers." (PMID 41281023, 2025).
nocardiosis (3 papers, 2022 to 2024). Nocardiosis is a local (skin, lung, brain) or disseminated (whole body) acute, subacute, or chronic bacterial infection. "Auto-Abs against cytokines have already been shown to underlie mycobacterial disease (type II IFN), mucocutaneous candidiasis (IL-17A/F), nocardiosis (GM-CSF), and staphylococcal disease (IL6)." (PMID 37196358, 2023). "Patients with auto-Abs against IL-6, IL-17, GM-CSF, and type II IFN are phenocopies of the corresponding inborn errors and underlie staphylococcal disease, mucocutaneous candidiasis, nocardiosis, and mycobacterial diseases, respectively." (PMID 35576468, 2022).
oligodendroglioma (3 papers, 2015 to 2022). A well-differentiated (WHO grade II), diffusely infiltrating neuroglial tumor, typically located in the cerebral hemispheres. "For example, genes located on chromosome 19q (oligodendroglioma, molecular type: IDH-mutated, 1p/1pq-codeleted) and genes located on 7p (NOD1, GSDME, IL6) could be altered by frequent 7p gains in molecular GBM." (PMID 35741587, 2022).
optic neuritis (3 papers, 2022 to 2025). Optic neuritis is inflammation of the optic nerve, the nerve that carries the visual signal from the eye to the brain.The conditionmay cause sudden, reduced vision in the affected eye(s). "rs1800795 has also been implicated in the development of optic neuritis risk, and in the modulation of flu-like symptoms in patients treated with interferon β1a; however, the role of most IL-6 gene SNPs in MS is still unknown." (PMID 35627281, 2022). "Patients with MOGAD showed higher IL6 (p = 0.036), IL8 (p = 0.012), and IL18 (p = 0.026) baseline levels compared with those with MS, in non–optic neuritis (ON) presentations." (PMID 39752619, 2025).
Optic neuropathy (3 papers, 2022 to 2024). "Experimental studies in various disease models addressed mechanisms of action and indicated modulation of neurotrophic factors (IGF-1, BDNF, CNTF, FGF-2, TNF-α) and immunomodulators (IL-10, IL-6, COX-2, NF-κB) by electrical stimulation of the eye in optic neuropathies." (PMID 35361287, 2022).
otitis (3 papers, 2018 to 2025). "Similarly, cinnamtannin B1, a trimeric A-type procyanidin, inhibits the O2•− generation and ELA-2 release by human neutrophils and reduces the infiltration of the immune cells and TNF-α and IL-6 release in vivo, e.g., in a mice ear infection model." (PMID 35630834, 2022). "TLR-1, -2, -4, -5, -6, -9; IL-6, -8, -10, -12; IFN-γ; TNF-α; and NOS mRNA expression was measured in effusions from both otitis-prone and non-otitis-prone groups." (PMID 40227356, 2025). "PBMC from children with CSLD have been found to produce less IL-6 and IFNγ in response to live NTHi challenge than healthy controls, but this was not apparent in the otitis-prone children in our study." (PMID 29621281, 2018).
panuveitis (3 papers, 2018 to 2024). A disorder characterized by inflammation of the entire uvea which includes the iris, ciliary body, and choroid. "Herein, we were able to demonstrate that increase of IL-6 also in intermediate, posterior and panuveitis." (PMID 35061677, 2022).
paraganglioma (3 papers, 2021 to 2025). A benign or malignant neoplasm arising from paraganglia located along the sympathetic or parasympathetic nerves. "To our knowledge, we report the first patients with increased IL-6 production in the presence of SDHD mutation related paragangliomas and lesions suspicious for metastases." (PMID 33715142, 2021). "In the workup of inflammation in a patient with known paragangliomas, IL-6 was measured and found to be elevated (23.0 pg/mL, reference range 0.43–8.87 pg/mL)." (PMID 33715142, 2021). "Thereafter, the combination of unexplained inflammation and the presence of paragangliomas raised the suspicion of an IL-6 producing paraganglioma." (PMID 33715142, 2021). "Paraganglioma is a less prevalent disease, and paraganglioma with only secreting interleukin-6 (IL-6) has not been previously reported." (PMID 37780619, 2023). "Previously reported IL-6 producing paragangliomas did also not show catecholamine excess, in line with our paraganglioma patients who had, like most head neck paragangliomas and SDHD mutation carriers, normal urinary normetanephrine excretion." (PMID 33715142, 2021).
paraplegia (3 papers, 2021 to 2024). Complete paralysis of the lower half of the body including both legs, often caused by damage to the spinal cord. "Results from this study support previous findings, given the large increase in IL-6 that occurred from pre- to post-exercise for persons with paraplegia (i.e., “very hard”) exercisers." (PMID 36188763, 2021). "Interestingly, within the SPG11–HSP cohort, there was a positive correlation of IL-6 levels to disease severity as measured by the SPRS (Spastic Paraplegia Rating Scale)." (PMID 38305941, 2024). "For example, a small-sized acute decrease in IL-6 was observed for persons with tetraplegia following exercise participation, whereas a medium-large acute increase in IL-6 was observed for persons with paraplegia." (PMID 36188763, 2021). "In a project studying individuals with SCI (paraplegia), an increased number of osteoclast-like cells in the iliac bone marrow culture compared with sternal bone marrow culture (as well as higher amounts of interleukin 6 (IL-6) in the iliac conditioned media) were reported." (PMID 33802713, 2021).
pelvic inflammatory disease (3 papers, 2020 to 2024). Pelvic inflammatory disease (PID) is an acute or chronic inflammation in the pelvic cavity. "The key target proteins for the SC and PS against pelvic inflammatory disease with dampness-heat stasis syndrome included vascular endothelial growth factor A (VEGFA), von willebrand factor (VWF), interleukin 6 (IL6), tumor necrosis factor (TNF) and nuclear transcription factor 1 (NFκB1)." (PMID 33424592, 2020).
pemphigus vulgaris (3 papers, 2008 to 2023). Pemphigus is a group of chronic autoimmune skin diseases characterized by blister formations on the outer layer of the skin and the mucous membranes. "As most studies on pemphigus vulgaris (PV) pathogenesis concern its active stage, we aimed to evaluate the serum concentration of TNF-α, IL-1, and IL-6 in PV patients in clinical remission." (PMID 18584045, 2008).
peritoneal adhesions (3 papers, 2012 to 2018). "We found that QLT-0267 decreased both the severity of peritoneal adhesion and the serum levels of IL-6 in our post-surgical adhesion mouse model." (PMID 29930281, 2018). "We therefore conclude that PE suppresses postoperative peritoneal adhesions by reducing TGF-β1 and IL-6 levels and the associated inflammatory reaction." (PMID 29212197, 2017). "In this study, we demonstrated that fibrin induced IL-1β, IL-6, TNFα and VEGF-A expression in PMCs, which could be attenuated by QLT-0267, and that QLT-0267 treatment could ameliorate post-surgical peritoneal adhesion." (PMID 29930281, 2018).
peritoneal disease (3 papers, 2012 to 2024). "These common effects of IL-6 provide insights into the shared mechanisms underlying the pathogenesis and progression of these diverse peritoneal diseases." (PMID 38689325, 2024). "IL-6 exerts diverse effects in different peritoneal diseases." (PMID 38689325, 2024). "Treatment of HGSC with cytokine or chemokine antagonists, eg anti-IL-6 antibodies 26, may be one way to delay or inhibit further development of peritoneal disease after diagnosis and initial chemotherapy and surgery." (PMID 22322968, 2012). "Therefore, an increased neutrophil count may be attributed to an upregulation of IL-6 due to peritoneal disease progression." (PMID 31238937, 2019).
Perthes disease (3 papers, 2018 to 2024). "Recent genetic study found significantly overrepresented heterozygous subjects with an IL-6 polymorphism in a control group compared to the Legg-Calvé-Perthes disease (childhood form of ischemic osteonecrosis) group." (PMID 29423066, 2018). "The findings of the present study were consistent with these reports, and revealed that the IL-6 gene was significantly upregulated in the rabbit model of Perthes disease." (PMID 37303951, 2023). "Recent studies investigating the genetic factors associated with Perthes disease have reported that the vascular endothelial growth factor (VEGF), Hypoxia Inducible Factor 1 (HIF1), and interleukin (IL)-6 are potential contributors to disease development." (PMID 37303951, 2023). "Another study reported that the protein level of the major proinflammatory cytokine IL-6 in synovial fluid was significantly elevated in Legg-Calvé-Perthes disease." (PMID 29423066, 2018). "Previous studies have demonstrated that certain cytokines, including IL-6, IL-1β, and tumor necrosis factor (TNF)-α, are overexpressed in individuals with Perthes disease." (PMID 37303951, 2023). "Notably, the DEGs identified in the rabbit model of Perthes disease in this study correlated with genes previously reported to be involved in inflammation [IL-6 and HIFa] and angiogenesis [PTGER2 and ALOX12] in Perthes disease." (PMID 37303951, 2023).
polyarteritis nodosa (3 papers, 2012 to 2022). Polyarteritis nodosa (PAN) is a rare, clinically heterogeneous, rheumatologic disease characterized by necrotizing inflammatory lesions affecting small- and medium-sized blood vessels. "It is worthy of note that IL-6 has been also implicated in the development of other types of vasculitis syndrome such as polyarteritis nodosa (PAN) and antineutrophil-cytoplasmic-antibody- (ANCA) associated vasculitis." (PMID 22315615, 2012).
polycystic kidney disease (3 papers, 2013 to 2025). A usually autosomal dominant and less frequently autosomal recessive genetic disorder characterized by the presence of numerous cysts in the kidneys leading to end-stage renal failure. "We demonstrate the value of KUPNetViz by two usage examples: the integration of calreticulin as a key player in a larger interaction network in renal graft rejection and the novel observation of the strong association of interleukin-6 with polycystic kidney disease." (PMID 23883183, 2013). "In addition, we propose a novel association of the inflammatory axis interleukin-6 (IL6)/IL6 receptor with the progression of polycystic kidney disease." (PMID 23883183, 2013). "While polycystic kidney disease is also accompanied with JSRD caused by ciliary abnormalities like ADPKD, the role of IL-6 signaling pathway in kidney disorders observed in JSRD has not yet been elucidated." (PMID 40570958, 2025). "The results also showed that IL6 and IL6R were up-regulated in both human polycystic kidney disease (PKD) and in a rat PKD model." (PMID 23883183, 2013).
polyneuropathy (3 papers, 2018 to 2025). A disease or disorder affecting more than one nerve. "Previous studies found an association between serum or gene expression levels of IL-6 and the duration or severity of polyneuropathy." (PMID 37638717, 2024). "It has been reported that the levels of serum biomarkers correlate with lower back pain and related functional impairment, and that the severity of polyneuropathy is associated with elevated tumor necrosis factor-alpha and interleukin-6 (IL-6)." (PMID 28361271, 2018). "Thus, IL-6 might be reflecting nerve fiber degeneration in polyneuropathies, in accordance with our findings." (PMID 37638717, 2024).
polyposis (3 papers, 2018 to 2021). "It is quite likely that, in the APC Min/+ model of polyposis, IL-33 promotes polyposis formation via Th2 cytokines IL-4 and IL-13 as well as inflammatory cytokine IL-6, which facilitate mast cell function." (PMID 29499051, 2018).
primary aldosteronism (3 papers, 2019 to 2023). An endocrine disorder characterized by excessive production of aldosterone by the adrenal glands. "To determine how glucose homeostasis is regulated by interactions of MR, IL-6 and GLP-1 in islets, we performed glucose tolerance and histological analysis of islets in primary aldosteronism (PA) model rodents and conducted in vitro experiments using α-cell lines." (PMID 31091693, 2019).
primary progressive MS (3 papers, 2020 to 2025). "Likewise, PBMCs from patients with primary progressive MS (PPMS) overexpress pro-inflammatory cytokines, including IL-1β, IL-6, TNF, and NLRP3, with monocytes being the primary driver of this profile." (PMID 40710307, 2025).
protein-energy malnutrition (3 papers, 2020 to 2025). A nutritional deficit that is caused by inadequate protein or calorie intake. "Protein-energy malnutrition, even of its subclinical form, is associated with the presence of elevated levels of proinflammatory cytokines such as TNF-α and IL-6, which play central roles in the pathophysiology of both nociceptive and neuropathic pain." (PMID 40917986, 2025).
pulmonary sarcoidosis (3 papers, 2015 to 2025). Sarcoidosis affecting the lung parenchyma. "Additionally, we have observed a trend towards increased levels of IL-8 (p = 0.05) and IL-6 (p = 0.05) in patients with pulmonary sarcoidosis." (PMID 25366387, 2015). "In addition, BAL levels of TNF-α and IL-6 are significantly higher in pulmonary sarcoidosis patients compared with control subjects." (PMID 25866481, 2015). "The serum levels of IL-6 and IL-1β were not significantly different between patients with pulmonary sarcoidosis or EPS or between healthy controls (data not shown)." (PMID 25866481, 2015).
radiculopathy (3 papers, 2012 to 2021). Disease involving a spinal nerve root (see spinal nerve roots) which may result from compression related to intervertebral disk displacement; spinal cord injuries; spinal diseases; and other conditions. "Further support regarding the contribution of IL-6 to sciatic pain was obtained from the discovery that genetic variations in IL-6 have a relationship with internal disc disruption (IDD)-related radiculopathy." (PMID 33853482, 2021). "Some studies have shown effect of tumour necrosis factor inhibitors or anti-interleukin 6 in patients with radiculopathy." (PMID 26635015, 2015).
retinal vasculitis (3 papers, 2017 to 2023). Inflammation of the retinal vasculature with various causes including infectious disease; lupus erythematosus, systemic; multiple sclerosis; behcet syndrome; and chorioretinitis. "As the increase in levels of IL-6 and IL-8 is associated with refractory retinal vasculitis in BD, intravitreal MTX could be effective in these patients." (PMID 34840688, 2021).